C3P1 (complement component 3 precursor pseudogene )
Synonyms: CPLP
Gene: Long non-coding RNA gene on chromosome 19 (10,041,841 to 10,074,770, forward strand). Ensembl gene ENSG00000291164.
Diseases named in the same sentence as C3P1 in open-access papers:
C3P1 is named in the same sentence as 8 diseases in open-access papers, as found by Europe PMC text mining. Sharing a sentence is not in itself a finding about the gene and the disease. The quoted sentences say what the papers report.
cholangiocarcinoma (1 paper, 2018). A carcinoma that arises from the intrahepatic biliary tree (intrahepatic cholangiocarcinoma) or from the junction, or adjacent to the junction, of the right and left hepatic ducts (hilar cholangiocarcinoma). "Diagnostic value of lncRNAs for Cholangiocarcinoma: HULC(b), H19(c), LPAL2(d), C3P1(e), AC005550.3(f), APOC1P1(g), PVT1(h),and sensitivity: Sen." (PMID 30305026, 2018).
coronary artery disease (1 paper, 2018). "rs6756513 is associated with platelet count and it had an edQTL in an intron of C3P1. rs10847434 is associated with coronary artery disease and had an edQTL with an editing site in the most 3′ exon of APOC1P1 in liver." (PMID 29527417, 2018).
gastric cancer (1 paper, 2021). A primary or metastatic malignant neoplasm involving the stomach. "For instance, circRNA C3P1 (circC3P1) regulates the miR-21/phosphatase and tensin homolog (PTEN) axis to restrain kidney cancer cell activity; circRNA HIAT1 (circHIAT1) regulates miR-21 to inhibit epithelial–mesenchymal transition (EMT) of gastric cancer (GC) cell lines." (PMID 34066762, 2021).
hepatoblastoma (1 paper, 2017). Hepatoblastoma (HB) is a malignant hepatic tumor and is the most common pediatric liver cancer. "Three genes identified in our hepatoblastoma analyses were also listed in the top 20 differentially methylated genes during liver development: CRP, NNMT (both hypermethylated) and C3P1 (hypomethylated)." (PMID 29228658, 2017).
tumor (1 paper, 2020). "UCKL1-AS1, LOC146880, UCA1, C3P1, LINC00261, and LINC01018 may be important in the progression of HCC and their expressions were detected in 20 patients with newly diagnosed HCC and their paired non-tumor liver tissue samples." (PMID 32201648, 2020).
C3P1 also shares sentences with these, for which no sentence is quoted: cancer (2 papers); hepatocellular carcinoma (1); lung carcinoma (1).